CD4 (CD4 molecule)
Diseases named in the same sentence as CD4 in open-access papers (continued):
Sharing a sentence is not in itself a finding about the gene and the disease.
lymphopenia (continued). "▪MAC infections have been documented among HSCT recipients, manifesting as cutaneous, pulmonary, or catheter-associated infections ▪For those with prolonged CD4+ lymphopenia who will be at risk of developing MAC, primary prophylaxis remains indicated." (PMID 39459894, 2024). "We found that Ripk1ΔCD4 mice display severe peripheral T cell lymphopenia, which is primarily mediated by a loss of naive CD4+ and CD8+ T cells, though cell numbers in the thymus were not reduced." (PMID 38734851, 2024). "Lymphopenia involves the loss of various lymphocyte classes, including CD4+ and CD8+ T cells, B cells, and natural killer cells." (PMID 39684323, 2024). "In contrast, syndromic EV has been associated with T cell deficiencies, sharing CD4+ T cell lymphopenia." (PMID 39339890, 2024). "In conclusion, we report a patient with STK4 deficiency diagnosed in his thirties, with HPV38-associated EV, CD4+ lymphopenia, lymphoma and EBV viremia." (PMID 39110273, 2024). "Bendamustine is an alkylating agent that causes prolonged lymphocytopenia, particularly CD4 T-cell depletion." (PMID 39723265, 2024). "The most important biological marker in guidelines to be considered as a risk factor of PCP is lymphopenia when the rate is lower than <1 G/L and associated with a decrease in CD4+ T lymphocytes." (PMID 38988362, 2024). "In this regard, lymphopenia, especially of CD4+ T cells, has been proposed as a risk factor for PML in SLE and other individuals." (PMID 37959410, 2023). "Utilizing T cell‐specific Rpa1‐deficient (Rpa1fl/fl Cd4‐cre) mice, loss of Rpa1 results in lymphopenia through restraining peripheral T cell population and limiting TCR repertoire diversity." (PMID 36721037, 2023). "Lymphopenia observed during the acute stage of COVID-19 disease is caused by CD4+ and CD8+ apoptosis." (PMID 36984473, 2023). "This contrasts to the acute phase in which lymphopenia is a predictive marker of disease severity and the occurrence of CD4+ T cell apoptosis is a confounding marker of the pathogenicity." (PMID 36997530, 2023). "Lymphopenia as a result of drastic loss of CD4+T cells occurs due to HIV-1 and SARS-CoV-2 infection and is considered a prognostic marker." (PMID 37243203, 2023). "Nonetheless, previous studies have implicated lymphopenia, especially of the CD4+ T-cell compartment, as a predisposing factor." (PMID 37959410, 2023). "STK4 homozygous mutations cause a deficiency associated with B cell lymphopenia and CD4 lymphopenia, particularly affecting naïve T cells, and signaling pathways important for T cell survival and death." (PMID 36960048, 2023). "Previous study has reported that lymphopenia, corticosteroids and a low count of CD4+ T cells are risk factors for the development of PJP in adults with autoimmune inflammatory disorders." (PMID 36829171, 2023). "SARS-CoV-2 infection is associated with lymphopenia, particularly in CD4+ T cells and CD8+ T cells, indicating abnormal immune function during SARS-CoV-2 infection." (PMID 37936709, 2023). "More recently, CD4+ T cell lymphopenia has emerged as a significant risk factor in TB-infected patients." (PMID 38004652, 2023). "Patients with PIDs predisposed to HPV-related disease, are predominantly associated with a CD4+ T cell lymphopenia, a decrease in CD8+ T cells and NK cells, and impaired TCR signaling; all factors important for targeting and eliminating HPV." (PMID 36960048, 2023). "Lymphopenia and low CD4+ T cell counts contribute to the risk of PJP in HIV patients, and guidelines for preventing PJP in HIV patients are based on CD4+ T count < 200 cells/μl." (PMID 36829171, 2023). "Highly expressed in lymphocytes, moesin determines the formation of the immunological synapse in B and T cells and controls the proliferation of CD8+ and CD4+ Tregs, whose deficiency has been found to result in persistent lymphopenia in the peripheral blood." (PMID 37711606, 2023).
lymphopenia (continued). "Without reporting a specific mutation, both patients — one diagnosed with SCID and the other with common variable immunodeficiency and CD4 lymphopenia — seemed to be heterozygous for the mutations and showed largely normal TCR signaling." (PMID 38112969, 2023). "On survival analysis, lymphopenia (<1.3 x 109/L) and a CD4 count <150 cells/ul were both significantly associated with a shorter survival time in the people living with HIV, while the monocyte count (>0.63 x 109/L) was not." (PMID 36630466, 2023). "Lymphopenia and a low CD4 + cell count have been consistently reported as risk factors for PCP, and several studies have addressed the recommendation of PJP prophylaxis in non-HIV-infected patients based on total lymphocyte and/or CD4 + lymphocyte count." (PMID 37439850, 2023). "Significant improvement in lymphopenia was associated with an increase in mean CD4+ and CD8+ lymphocyte counts of 20% (P = 0.06) and 15% (P < 0.05), respectively." (PMID 35255966, 2022). "Prolonged discontinuation from ART is associated with persistent viremia as well as progressive CD4 lymphopenia and disease progression." (PMID 36072945, 2022). "The critical role of CD4 T cell in antitumor immunity is supported by the poor prognosis associated with CD4 T lymphopenia in several cancers." (PMID 35546670, 2022). "Studies have shown that lymphopenia occurs due to the decline in CD4+ and CD8+ T cells caused by multiple factors." (PMID 36556258, 2022). "In the present study, we identified the CD4+ T lymphopenia (count < 500/μL) as a poor prognostic factor associated with a high risk of death in NSCLC." (PMID 35546670, 2022). "Each of the patients had (CD4+) lymphopenia as the precipitating cause of PML, either idiopathic (n = 3) or due to an underlying disease elsewhere (sarcoidosis (n = 1), HIV infection (n = 1), hematologic disease (n = 2))." (PMID 34994851, 2022). "When present, lymphopenia specifically related to low CD4+ T-cell counts, has been linked with greater inflammatory activity in sarcoidosis." (PMID 36311769, 2022). "Identifiable risk factors for IRIS development include a high pre-ART HIV viral load, advanced immunosuppression associated with severe CD4+ lymphopenia, as well as a short interval between antitubercular treatment (ATT) and ART." (PMID 35432354, 2022). "CD4+ lymphopenia has been associated with the expression of markers of chronic activation in heavy drinkers and with the expression of markers of immunosenescence in alcohol-related cirrhosis." (PMID 35054000, 2022). "Our findings highlighted the importance of CD4+ T lymphocyte counts and potential sepsis-associated lymphopenia in the diagnosis and treatment of sepsis and support the addition of lymphocyte subset analysis to the clinical interpretation of mNGS results." (PMID 36453923, 2022). "NGS sequencing of a group of patients with CID features associated with CD4 lymphopenia revealed DOCK2 deficiency in 3 patients and CARD11 deficiency in 3 patients." (PMID 35655284, 2022). "HIV infection is a complex, multifactorial disease, in which, besides CD4+ T-cell lymphopenia, people present chronic immune activation associated with viral replication and bacterial translocation." (PMID 36483556, 2022). "In some cats, lymphopenia is characterized by the preferential loss of CD4+ T cells, resulting in an inverted CD4+/CD8+ ratio (comparable to FIV infection), but more commonly, substantial losses of both CD4+ and CD8+ T cells occur." (PMID 35632665, 2022). "Increased percentages of MDSCs in peripheral blood mononuclear cells (PBMC) were associated with CD4+ T cell lymphopenia." (PMID 35733812, 2022).
lymphopenia (continued). "Previous studies have reported that CD4 lymphopenia was associated with poor prognosis in cancer patients, but these studies did not include patients with lung cancer." (PMID 35546670, 2022). "On the other hand, CD4+ T cell lymphopenia has also been reported in STK4-deficient patients in the absence of detectable EBV infection." (PMID 34427831, 2021). "Fingolimod is a S1P1 receptor modulator that prevents activated lymphocyte egress from lymphoid tissues causing lymphopenia, mainly affecting CD4+ T lymphocytes." (PMID 33530945, 2021). "Before treatment, Ob2 and Ob3 patients exhibited CD4+ lymphopenia and deficient lymphocyte activity; however, the therapy with the synthetic leptin addressed these issues, and both patients showed normal immunophenotype." (PMID 34504472, 2021). "Lymphopenia and more specifically CD4+ lymphopenia are also associated with active sarcoidosis and the deeper the lymphopenia, the more severe the sarcoidosis." (PMID 34359324, 2021). "Participants who are severely zinc-deficient suffer from lymphopenia, a decreased CD4/CD8 ratio, decreased natural killer (NK) cell activity, and increased monocytic cytotoxicity." (PMID 34966750, 2021). "Lymphopenia is primarily driven by loss of CD4+ and CD8+ T cells subsets, which result from spontaneous apoptosis but not pyroptosis." (PMID 34869652, 2021). "Lymphopenia caused by TMZ is said to be characterized by depletion of a particularly high proportion of CD4-positive helper T cells." (PMID 34320929, 2021). "A rarer form of combined immunodeficiency affecting older adults, the Late-Onset Combined Immunodeficiency (LOCID, 5–8% of CVID cohorts) is characterized by CD4 lymphopenia (naive T cells) and an increased susceptibility to opportunistic infections." (PMID 34359324, 2021). "Impaired immune response to neoantigens contained in vaccines and new infections, a common clinical challenge among HCV and HIV infected individuals and the elderly, has been linked to naïve CD4+ lymphopenia." (PMID 35062255, 2021). "The word “lymphopenia” refers to a reduction in the peripheral lymphocyte count (primarily CD4 + T and CD8 + T cells); this condition increases the risk of secondary bacterial infections." (PMID 34444600, 2021). "Full Treg reconstitution prevents the rapid oligoclonal proliferation that gives rise to pathogenic CD4+ effector T cells, while preserving the slow homeostatic form of lymphopenia-induced peripheral expansion that repopulates a diverse peripheral T-cell pool." (PMID 35087775, 2021). "The majority of CD4+ T cells acquired a memory phenotype (CD44highCD62LlowCD25−), which is a hallmark of lymphopenia-induced proliferating cells." (PMID 33923792, 2021). "Age and cirrhosis -associated naïve CD4+ lymphopenia is present both before and after HCV DAA therapy." (PMID 33912168, 2021). "Patients with STK4/MST1 deficiency have a profound CD4 lymphopenia with very low circulating naive CD4 and CD8 T cells." (PMID 34867982, 2021). "Chronic hepatitis C virus (HCV) infection is associated with naïve CD4+ T cell lymphopenia and long-standing/persistent elevation of cellular and soluble immune activation parameters, the latter heightened in the setting of HIV co-infection." (PMID 35062255, 2021). "Previous studies suggested that acute or chronic VL can cause CD4 lymphopenia and a low CD4:CD8 ratio in the blood, whereas CD4 levels were increased in the bone marrow." (PMID 34688312, 2021). "Cumulatively, these data indicate that numerical loss, due to sepsis-induced lymphopenia, of naive autoantigen-specific CD4 T cell precursors is sufficient to explain the protective effect of CLP on EAE disease." (PMID 33191915, 2020). "The current work also takes it to the next level by showing that adoptive transfer of a population of antigen-experienced, Treg-containing CD4+ T cells, can prevent lymphopenia-associated spontaneous EAU in dTg HEL/TCR mice." (PMID 33013877, 2020).
lymphopenia (continued). "From the little we know in the inflammatory response triggered by SARS-CoV-2, during this infection lymphopenia is observed, with loss of CD4 + and CD8 + T cells, hyperproduction of IL6, IL10, IL2R, TNFa and CCL2." (PMID 32883368, 2020). "Our group also reported studies showing associations between thymic function and infections and CD4 T cell lymphopenia and cardiovascular events and death." (PMID 32903778, 2020). "We previously showed that GG treatment attenuates lymphopenia and restore the loss of CD4+ and CD8+ T cells in sepsis by inhibiting the expression of cleaved caspase-3 and caspase-8." (PMID 32677895, 2020). "Here we show lymphopenia, selective loss of CD4+ T cells, CD8+ T cells and NK cells, excessive T-cell activation and high expression of T-cell inhibitory molecules are more prominent in severe cases than in those with mild disease." (PMID 32641700, 2020). "Herein, we report on a case of disseminated varicella zoster infection after post-partum vaccination in a patient found to have CD4 lymphopenia and eventually diagnosed with ALPS caused by a novel germline missense mutation in FAS death-domain." (PMID 31191551, 2019). "Those modifications of the EBV-specific T cell response were associated with a profound CD4+ T cell lymphopenia in KTRs compared to HCs, involving the naïve CD4+ T cell subset, and a persistent activation of highly-differentiated senescent CD8+ T cells." (PMID 31639143, 2019). "This is in line with peripheral lymphocyte deficiencies and CD4 lymphopenia observed in glioblastoma patients, indicating a systemic immune suppression." (PMID 30972297, 2019). "Isolated CD4 lymphopenia has been described with MHC Class II deficiency (RFXANK, CIITA, RFXAP) and hypomorphic RAG variants." (PMID 31572360, 2019). "Itk deficiency can lead to CD4 lymphopenia and Epstein-Bar virus (EBV)-associated lymphoproliferation and recurrent pulmonary infections in humans." (PMID 32038633, 2019). "In animal models, cocaine administration leads to lymphopenia, with a significant decline in T, B, and NK cells, causing a disproportional number of lymphocytes subsets and resulting in elevated CD4/CD8 ratio in peripheral blood." (PMID 31749792, 2019). "The loss of the Th1 effector/effector memory latent specific CD4+ T cells is in line with the total CD4+ T cell lymphopenia observed in KTRs, and evokes a new mechanism for predisposition to EBV-related complications in this immunosuppressed population." (PMID 31639143, 2019). "Chronic HEV infection has been associated with lymphopenia, a low CD4 T cell count and impaired HEV-specific T cell response." (PMID 30813268, 2019). "In an attempt to identify immunological correlates and/or underlying mechanisms for CD4 lymphopenia in ALPS-FAS, we compared the immunophenotypic characteristics and plasma cytokine levels of patients with ALPS-FAS with or without CD4 T-cells lymphopenia." (PMID 31191551, 2019). "Lymphopenia, a common feature of viral hemorrhagic fever with loss of CD4+, CD8+ T cells and NK cells, is considered to be due to apoptosis mediated by pro-inflammatory cytokines and NO produced by monocytes/macrophages." (PMID 31725732, 2019). "In contrast, the expression of other molecules previously associated with CD4 lymphopenia, such as CD3 and HLA-DR, was normal and comparable to that observed in healthy donors (data not shown)." (PMID 31781092, 2019). "Wolfe and Peacock described that lymphopenia and low CD4+T cell count are risk factors of pneumocystis pneumonia in connective tissue diseases." (PMID 30994732, 2019). "Although CD4+ lymphopenia is a powerful marker of reduced survival, its causes remain uncertain and need to be better investigated (tumor or host origin, inter-relation with TILs...)." (PMID 30922400, 2019).
lymphopenia (continued). "Immunologically, CD4+ T cell and B cell lymphopenia, progressive loss of naïve CD4+ and CD8+ T cells, expansion of senescent CD8+ T cells, reduced class-switched memory B cells, and poor antibody responses are common findings." (PMID 29988375, 2018). "For instance, CD4+ T-cell lymphocytopenia has been associated with PML in the context of HIV; however, simply monitoring absolute changes in a single specific subset is also insufficient." (PMID 29456537, 2018). "Although CD4 lymphopenia is often idiopathic, previous studies showed that medical conditions associated with CD4 lymphopenia in HIV-negative individuals include cirrhosis and other advanced liver disease." (PMID 30315476, 2018). "We report the case of a patient with acute necrotizing colitis due to invasive amebiasis associated with CD4 lymphopenia and impaired neutrophil responses." (PMID 28243230, 2017). "Increased IgM levels (78%), IgG deficiency (43%), and CD4 lymphopenia (84%) were significant immunologic features." (PMID 27555459, 2017). "Our finding of sustained severe long-term CD4 T-cell lymphopenia in X-linked CGD calls attention to the occurrence of major T-cell imbalances in the context of burst oxidative defects and raises the possibility of T-cell immunological exhaustion." (PMID 28553289, 2017). "The LCK deficiency is associated to naive CD4+ T-cell lymphopenia, respiratory tract infections, and early-onset autoimmune inflammation." (PMID 28448599, 2017). "Immunological hallmarks of zinc deficiency are thymic atrophy, lymphopenia, especially decreased CD4+ T helper (Th) cell numbers, resulting in a decreased CD4+/CD8+ ratio." (PMID 29064429, 2017). "The high production of the cytokines IL-10 and IL-5 with CD4 lymphopenia is likely to be a cause of the aggressive disease and the pulmonary spread." (PMID 27711109, 2016). "We studied three siblings with early childhood onset of CID characterized by CD4 lymphopenia and marked susceptibility to opportunistic and bacterial infection." (PMID 26801501, 2016). "First, studies in infants with overt CD4+ T cell lymphopenia and reversed CD4/CD8 T cell ratios, due to deficiency in the tyrosine kinase p56lck, showed that the peripheral CD8+ T cell pool was made up almost entirely of CD8+ T cells with the Tem phenotype." (PMID 28096804, 2016). "In this model, naïve CD4 effector T cells (CD4+CD25-CD45RBhi) adoptively transferred into Rag1-deficient mice undergo lymphopenia-induced expansion and cause intestinal inflammation that recapitulates human IBD." (PMID 25781948, 2015). "We found a trend towards association between lymphopenia at diagnosis of Hodgkin lymphoma and CD4 decline in the 12 months prior to diagnosis (p = 0.11)." (PMID 24504076, 2014). "Common immunological features in ITK deficient patients are progressive hypogammaglobulinemia and beside global lymphopenia, a progressive loss of CD4+ T cells." (PMID 25339095, 2014). "Taken together, we here describe for the first time JAK3 deficiency due to a hypomorphic JAK3 mutation and with somatic chimerism, causing a phenotype of T-cell deficiency evolving into predominant CD4 lymphopenia." (PMID 25205547, 2014). "In order to examine the potential role for PD-1:PD-L1interaction in lymphocyte apoptosis, one possible cause of lymphopenia in sepsis, we investigated the correlation between PD-1 expression on CD4 and CD8 T cells and absolute numbers of CD 4 and CD8 T cells." (PMID 24387680, 2014). "Here, we had used two different methods to induce CD4+ T cell-lymphopenia in mice; one by genetic deficiency of CIITA, the other by treatment with depleting antibody." (PMID 24466045, 2014). "Reactivation of parasites in this case is likely to have occurred in the setting of declining immune function, caused by advancing age and CD4 lymphopenia." (PMID 25428722, 2014).